SNORA74 (Small nucleolar RNA SNORA74 )
Gene: Small nucleolar RNA gene on chromosome 17 (14,177,131 to 14,177,310, forward strand). Ensembl gene ENSG00000252305.
Homologues: Orthologues: chimpanzee SNORA74 (99% identical), tropical clawed frog SNORA74 (59% identical), tropical clawed frog SNORA74 (58% identical), tropical clawed frog SNORA74 (57% identical), tropical clawed frog SNORA74 (46% identical). Paralogues in human: SNORA74 (98% identical), SNORA74B (82% identical), SNORA74C-2 (79% identical), SNORA74C-1 (79% identical), SNORA74A (52% identical), SNORA74 (48% identical), SNORA74 (32% identical), SNORA74D (27% identical).